PSMA5 (proteasome 20S subunit alpha 5)
Description:
Component of the 20S core proteasome complex involved in the proteolytic degradation of most intracellular proteins. This complex plays numerous essential roles within the cell by associating with different regulatory particles. Associated with two 19S regulatory particles, forms the 26S proteasome and thus participates in the ATP-dependent degradation of ubiquitinated proteins. The 26S proteasome plays a key role in the maintenance of protein homeostasis by removing misfolded or damaged proteins that could impair cellular functions, and by removing proteins whose functions are no longer required. Associated with the PA200 or PA28, the 20S proteasome mediates ubiquitin-independent protein degradation. This type of proteolysis is required in several pathways including spermatogenesis (20S-PA200 complex) or generation of a subset of MHC class I-presented antigenic peptides (20S-PA28 complex).
Synonyms: ZETA; PSC5
Tractability: Small molecule: an approved drug acts on it; a structure with a bound ligand is known; a high-quality ligand is known; it belongs to a druggable protein family. Antibody: its Gene Ontology location is reachable by antibodies, with high confidence. PROTAC: ubiquitination databases record sites on it; its protein half-life has been measured; a small molecule that binds it is known.
Gene: Protein-coding gene on chromosome 1 (109,399,042 to 109,426,471, reverse strand). Ensembl gene ENSG00000143106.
Subcellular location: Cytoplasm; Nucleus
Subcellular location (Human Protein Atlas): Cytosol
Pathways (Reactome):
Immune System: AMPK-induced ERAD and lysosome mediated degradation of PD-L1(CD274); Activation of NF-kappaB in B cells; Antigen processing: Ub, ATP-independent proteasomal degradation; Antigen processing: Ubiquitination & Proteasome degradation; CLEC7A (Dectin-1) signaling; Cross-presentation of soluble exogenous antigens (endosomes); Dectin-1 mediated noncanonical NF-kB signaling; Downstream TCR signaling; ER-Phagosome pathway; FCERI mediated NF-kB activation; GSK3B-mediated proteasomal degradation of PD-L1(CD274); Interleukin-1 signaling; NIK-->noncanonical NF-kB signaling; Neutrophil degranulation; SPOP-mediated proteasomal degradation of PD-L1(CD274); TNFR2 non-canonical NF-kB pathway
Cell Cycle: APC/C:Cdc20 mediated degradation of Securin; APC/C:Cdh1 mediated degradation of Cdc20 and other APC/C:Cdh1 targeted proteins in late mitosis/early G1; Autodegradation of Cdh1 by Cdh1:APC/C; Autodegradation of the E3 ubiquitin ligase COP1; Cdc20:Phospho-APC/C mediated degradation of Cyclin A; FBXL7 down-regulates AURKA during mitotic entry and in early mitosis; G2/M Checkpoints; SCF(Skp2)-mediated degradation of p27/p21; SCF-beta-TrCP mediated degradation of Emi1; Separation of Sister Chromatids; The role of GTSE1 in G2/M progression after G2 checkpoint; Ubiquitin-Mediated Degradation of Phosphorylated Cdc25A; Ubiquitin-dependent degradation of Cyclin D
Signal Transduction: Asymmetric localization of PCP proteins; Degradation of AXIN; Degradation of DVL; Degradation of GLI1 by the proteasome; Degradation of GLI2 by the proteasome; Degradation of beta-catenin by the destruction complex; GLI3 is processed to GLI3R by the proteasome; Hedgehog 'on' state; Hedgehog ligand biogenesis; MAPK6/MAPK4 signaling; Negative regulation of NOTCH4 signaling
and 29 more pathways
Gene Ontology:
Molecular function: protein binding; structural constituent of proteasome
Biological process: proteasomal protein catabolic process; proteasome-mediated ubiquitin-dependent protein catabolic process; regulation of proteasomal protein catabolic process; response to oxidative stress; apoptotic process; CD8-positive, alpha-beta T cell differentiation; CD8-positive, alpha-beta T cell homeostasis; cellular response to type I interferon; DNA damage response; DNA repair; flagellated sperm motility; immune system process; meiotic cell cycle; negative regulation of regulatory T cell differentiation; positive regulation of interleukin-2 production; positive regulation of tumor necrosis factor production; positive regulation of type II interferon production; proteasomal ubiquitin-independent protein catabolic process; regulation of G1/S transition of mitotic cell cycle; response to type II interferon; spermatogenesis; T-helper 1 cell differentiation; T-helper 17 cell differentiation; thymic T cell selection; protein catabolic process; and 1 more
Cellular component: cytoplasm; cytosol; extracellular exosome; nucleus; proteasome complex; proteasome core complex; proteasome core complex, alpha-subunit complex; extracellular region; ficolin-1-rich granule lumen; nucleoplasm; proteasome storage granule; secretory granule lumen; spermatoproteasome complex; synaptic vesicle
Genetic constraint (gnomAD): Loss-of-function variants: 3 observed, 24.33 expected, observed/expected ratio (o/e) 0.12, 90% interval 0.055 to 0.32. The upper end of that interval is the gene's LOEUF score, 0.32, which puts it in group 1 of 6, group 1 being the genes least tolerant of losing a copy. Missense variants: 101 observed, 246.91 expected, observed/expected ratio (o/e) 0.41, 90% interval 0.35 to 0.48. Synonymous variants: 78 observed, 84.59 expected, observed/expected ratio (o/e) 0.92, 90% interval 0.77 to 1.11.
Homologues: Orthologues: chimpanzee PSMA5 (100% identical), dog PSMA5 (100% identical), guinea pig PSMA5 (100% identical), macaque PSMA5 (100% identical), mouse Psma5 (100% identical), pig PSMA5 (100% identical), rat Psma5 (100% identical), rabbit PSMA5 (99% identical), zebrafish psma5 (96% identical), tropical clawed frog psma5 (84% identical), Drosophila melanogaster Prosalpha5 (71% identical), Caenorhabditis elegans pas-5 (62% identical). Paralogues in human: PSMA8 (37% identical), PSMA4 (35% identical), PSMA7 (35% identical), PSMA3 (32% identical), PSMA2 (31% identical), PSMA1 (30% identical), PSMA6 (26% identical), PSMB10 (21% identical), PSMB7 (21% identical), PSMB6 (19% identical), PSMB9 (17% identical), PSMB1 (16% identical), and 6 more.